MMP9 (matrix metallopeptidase 9)
Diseases named in the same sentence as MMP9 in open-access papers (continued):
Sharing a sentence is not in itself a finding about the gene and the disease.
tumor (continued). "MMP9 is a member of the matrix metalloproteinase family, which has a role in degradation of the extracellular matrix and promotes tumor invasion and metastasis." (PMID 32029730, 2020). "The results showed that MMP9 expression was higher in primary tumor samples than in normal samples, and the MMP9 expression level was relatively increased with the increased level of HCC grade and stage." (PMID 31956374, 2020). "A previous study also identified a correlative relationship between NSCLC metastasis with tumor MMP9 expression." (PMID 33119681, 2020). "We verified fluorescence imaging by analysing MMP9 expression in tumour lysates plus gross histology." (PMID 32655131, 2020). "Large T-EVs likewise harbour abundant bioactive molecules associated with regional invasion (such as ARF6, Cav-1, MMP9, and MMP2), and their abundance is also associated with tumour development." (PMID 33081785, 2020). "In the same tumor tissue, the expression levels of markers associated with angiogenesis (VEGF1) and migration (MMP-9 and E-CAD) were also evaluated." (PMID 31963392, 2020). "The results from several studies indicate that MMP-9 mainly cooperates with the αvβ3 integrin to promote tumor cell motility." (PMID 32630531, 2020). "In this study, high MMP9 mRNA expression was associated with poor prognostic parameters including higher tumour grade, ER-/PR-, HER 2 + tumours and TNBC tumours." (PMID 32445177, 2020). "The induction of NETosis involves mechanisms that are activated by HMGB1/TLR4 interactions and tumor-derived IL-8, respectively; NETs enhance tumor invasion via the presentation of proteolytic enzymes, such as MMP-9 and elastase." (PMID 32664328, 2020). "Taken together, these data indicate that neutrophil‐produced MMPs, including MMP9, contribute to the tumor‐promoting TME by activating TGFβ, which inhibits tumor‐infiltrating effector T‐cell activity and is favorable for Tregs." (PMID 31793740, 2020). "Matrix metalloproteinases, particularly MMP‐2 and MMP‐9, are crucial molecules in tumor development, progression, and metastasis." (PMID 32180962, 2020). "Incubation of astrocytes with EVs from any of the tumor conditions increased active MMP9 levels by approximately 7- to 14-fold (p < 0.05)." (PMID 32033611, 2020). "AURKA overexpression was also suggested to increase the expression of MMP-2, MMP-7, MMP-9, leading to tumor metastasis by degrading extracellular matrix proteins." (PMID 33245732, 2020). "MMP-9 is a matrix remodeling enzyme expressed in alveolar macrophages, granulocytes and mast cells that plays essential roles in leukocyte migration and tumor cell metastasis among others." (PMID 32528529, 2020). "The experimental results suggested that the high expression of MMP-9 in tumor cells promoted the occurrence of EMT by increasing the expression of Vimentin and reducing the expression of E-cadherin." (PMID 32698816, 2020). "Next, we analysed the expression of genes such as Vegf, Mmp9, and Cxcl1, which are known to play an important role in tumour progression and metastasis." (PMID 32025027, 2020). "Taken together, these results mechanistically elucidate the tumor-suppressive role of MMP9 in CAC by promoting genomic stability." (PMID 32943603, 2020). "Western blot analysis further indicated that inhibition of miR-183-5p led to a down-regulation in the expression of VEGFA, VEGFAR2, ANG2, PIGF, MMP-2 and MMP-9 along with up-regulated FOXO1 expression in tumor tissues (p < 0.05)." (PMID 32364530, 2020). "MMP9, also known as gelatinase B, plays an important role in extracellular matrix (ECM) remodelling, protein cleavage, and is associated with tumour invasion, metastasis and modulation of tumour microenvironment." (PMID 32445177, 2020). "Our results, along with previous reports, suggest that MMP9 and Src are involved in tumour FFAs metabolic microenvironment and are important for FFAs to contribute to tumour spread." (PMID 31657086, 2020).
tumor (continued). "Tumor-associated neutrophils derived factors such as VEGF and MMP9 contribute to tumor angiogenesis and metastasis." (PMID 32632106, 2020). "Specifically, the MMP-9 produced by metastatic tumor cells and metastasis-infiltrating neutrophils and/or macrophages breaks down the vessel basement membrane and perivascular matrix, thereby generating ECM fragments." (PMID 32630531, 2020). "The protein expression of N‐cadherin, vimentin, MMP‐2 and MMP‐9 was profoundly elevated in tumours of nude mice injected with oe‐HAND2‐AS1 + sh‐E2F4 and oe‐HAND2‐AS1 + oe‐C16orf74 (P < .05)." (PMID 32314545, 2020). "It is clear that PCNA, CyclinD1, MMP2, and MMP9 are downstream effectors of PI3K/AKT pathway involved in tumor invasion and growth." (PMID 33093458, 2020). "Metalloproteinases, specifically MMP-2 and MMP-9, are usually involved in the extracellular matrix disruption that allows tumor cell migration and invasion." (PMID 32158394, 2020). "Because the main component of extracellular matrix basement membrane is type IV collagen, MMP-2 and MMP-9 play a key role in the degradation of extracellular matrix and promotion of tumor invasion and metastasis." (PMID 31938018, 2020). "Expression of additional mediators of tumor growth, including MMP9 and Gas6 is also induced by gal-8." (PMID 32355198, 2020). "Neutrophils are the major contributors of MMP9 in the tumor microenvironment and contributors of MMP2 during chronic inflammation." (PMID 33049964, 2020). "We recently proposed a potent drug repurposing of anti-malaria drug artesunate (ART) for an anticancer agent that effectively reduced both the viability of a tumor-like organoid (tumoroid) and the activities of the MMP9 promoter." (PMID 32102440, 2020). "Matrix metalloproteinases-9 (MMP-9) is one of the most important enzymes to breakdown extracellular matrix which plays a major role in tumor invasion and metastasis." (PMID 32944046, 2020). "Numerous reports have suggested that MMP-9 expression/activity regulation and tumor development and progression are critically mediated by MAPK signaling pathway." (PMID 32492880, 2020). "The solubilized growth factors, together with inflammatory mediators and additional growth factors released by tumor-infiltrating leukocytes, further stimulate the cells constituting the carcinoma mass to generate additional MMP-9." (PMID 32630531, 2020). "MMP9 has been shown to modulate distinct steps in the metastatic cascade including tumor invasion, metastatic niche formation, angiogenesis, and metastatic colonization of secondary sites." (PMID 33119681, 2020). "The inhibition of miR-21 causes the suppression of tumor cell invasiveness via the HIF-1/VEGF pathway and the downregulating of MMP-2 and MMP-9." (PMID 33321819, 2020). "In particular, MMP-9 is known to boost angiogenesis and stimulate tumor neovasculature by increasing the bioavailability of VEGF." (PMID 31690961, 2020). "It has significant inhibitory effect on tumor metastasis target matrix metalloproteinase-9 (MMP-9) and cyclooxygenase-2 (COX-2), with IC50 values of 11.2 and 2.2 μmol/L, respectively." (PMID 32825106, 2020). "Together with the data obtained using DDR1-IN-1, these results indicate that AKT and ERK phosphorylation rates, MMP9 expression and tumor cell proliferation are modified by DDR1 signaling and/or by DDR1 expression." (PMID 32090682, 2020). "Various pro-angiogenic factors, such as vascular endothelial growth factor (VEGF), fibroblast growth factor (FGF) and matrix metallopeptidase 9 (MMP-9), are secreted to participate in the process of tumor angiogenesis." (PMID 33363016, 2020). "The overall tendencies were matched with mRNA expression, but leptin and knockdown of CTSA significantly upregulated MMP9 (matrix metalloproteinase 9), a biomarker of tumor invasion and metastasis." (PMID 33255835, 2020). "MMP-2 and MMP-9 play an important role in tumor development progression by promoting migration and invasion." (PMID 33311443, 2020).
tumor (continued). "Studies have shown that the mechanism of microvessel proliferation and basal membrane degradation in other diseases, such as cancers and strokes, involves the JAK2/STAT3, IL-6/JAK2/STAT3, and MMP-9 pathways, which regulate the progression of tumor metastasis." (PMID 32047820, 2020). "Knocking down HMGN5 decreased the expression of Bcl-2, Cyclin D1, MMP-2, and MMP-9 and increased the expression of Bax and p21 which is related to the malignant phenotype of tumor proliferation, migration, and invasion." (PMID 32596388, 2020). "Several molecules (NE, MMP9, Bv8) expressed on neutrophils can mediate their positive roles in tumor proliferation." (PMID 33343560, 2020). "Several studies have demonstrated that the up-regulation of MMP-9 is strictly influenced by several genetic alterations or modifications of the tumor microenvironments." (PMID 32392801, 2020). "Consistently, inhibition of PlGF by a small short hairpin interfering RNA decreased the levels of MMP9 and tumor invasiveness." (PMID 32085654, 2020). "Consistent with the disruption of the BSCB, remarkably increased levels of IL-1β, TNF-α and MMP9 were observed in the tumor group of mice." (PMID 32796132, 2020). "Our result indicates a differential expression of MMP9 activity in neutrophils under the chemotherapy-resistant and parental tumor microenvironments." (PMID 33049964, 2020). "It has been shown that elevated expression of MMP2 and MMP9 is positively correlated with tumor progression, metastasis, and poor prognosis." (PMID 32194780, 2020). "MMP9 knockout mice exhibited reduced keratinocyte hyperproliferation and bone marrow transplantation of MMP9 expressing cells can restore the tumor growth in these mice." (PMID 33343560, 2020). "Expression of LMP1 has been shown to induce MMP1 and MMP9 implicating the viral oncoprotein in contributing to tumor metastasis." (PMID 33382850, 2020). "The expression levels of several cytokines including SCF, MCP-1, granulocyte-colony stimulating factor (G-CSF), sTNF-R1, and pro-MMP-9 were increased in the serum of tumor-bearing mice." (PMID 32647215, 2020). "We found that the mRNA expression levels of FABP5, FASN, HSL, TWIST1, VEGF-C, and MMP9 were significantly higher in tumours of the bevacizumab group than those of the control group." (PMID 32550890, 2020). "M2-like TAMs contribute to tumor progression by expressing VEGFα to benefit angiogenic process, producing MMP9 to promote tumor invasion, secreting IL-10 and TGFβ to maintain an immunosuppressive microenvironment." (PMID 33260160, 2020). "Infiltration of malignant tumor cells is aided by high expression of CD147, which can increase MMP-9 activity to cause degradation of the ECM and the basement membrane of cells." (PMID 32377273, 2020). "Here, we tackled MMP-9 because of its confirmed role in tumor invasion, metastasis, angiogenesis, and immuno-response, making it an ideal target for cancer therapy." (PMID 32492898, 2020). "Mo-MDSC also has a high expression of MMP-9, an enzyme that supports migration, invasion and angiogenesis in the tumor." (PMID 32466280, 2020). "We found that MMP9 was significantly upregulated in testicular SEM tissues and associated with tumor stage." (PMID 33659208, 2020). "Studies have shown that COMP can increase the ability of tumor cells to degrade the surrounding ECM stroma and enhance EMT by upregulating the expression of MMP9, thereby promoting tumor metastasis." (PMID 32754278, 2020). "MMP9 synthesized by macrophages upon cues from tumour cells allows for invasion by disruption of the extracellular matrix." (PMID 32735377, 2020). "MMP9, a member of the zinc‐dependent proteolytic enzymes, is essential for local proteolysis of the extracellular matrix and tumor metastasis." (PMID 33377649, 2020). "The extrinsic mechanisms leading to MMP-9 upregulation mainly refer to hypoxia or inflammation, which often coexist at the tumor site." (PMID 32630531, 2020).
tumor (continued). "Matrix metalloproteinase 9 (MMP9) is one of the zinc-dependent endopeptidase family, and is synthesized by both tumor and peritumoral stromal cells." (PMID 32784500, 2020). "Our results showed that overexpression RIP3 led to significantly decreased MMP-2 and MMP-9 levels, which inhibited the progression of the tumor." (PMID 32984054, 2020). "Tumor–infiltrating neutrophils are a source of matrix metalloprotease 9 (MMP-9) promoting remodeling of extracellular matrix (ECM) and neovascularization." (PMID 33363012, 2020). "CCL5 induces MMP-9 secretion and collagen degradation by monocytes, supporting tumor cell extravasation." (PMID 32630699, 2020). "Then, exosomes released by tumor cells augment MMP-9 production by partner tumor cells or normal cells which reside in the colonized site(s)." (PMID 32630531, 2020). "Further study demonstrated that matrix metalloprotease 9 (MMP-9) produced by TAMs contributed to tumor angiogenesis in the tumor tissue and that the parasite-induced reduction in MMP-9 expression in TAMs resulted in the suppression of tumor angiogenesis." (PMID 32972437, 2020). "MMP9 is a well-known tumor promotor and mainly enhances the invasion and metastasis of various tumors." (PMID 33659208, 2020). "Its expression in tumors is a negative prognostic factor and it is generally associated with an increase in tumor proliferation and invasiveness supported also by the OPN-induced MMP-9 over-expression." (PMID 32392801, 2020). "Tumor cell MVs promote MMP-9 and ERK1/2 phosphorylation in fibroblasts to induce chemoresistance and migration; in turn activated fibroblasts secrete MVs carrying CX3CL1 that more strongly promote migration/invasion of cancer cells expressing CX3CR1." (PMID 32957712, 2020). "In the same model, thujone also inhibited in vitro secretion of MMP-2 and MMP-9 and the adhesion of tumor cells to the collagen-coated plate, as well as cell invasion and migration." (PMID 32948083, 2020). "Another player regulated by MYC in tumor microenvironment that has a distinct role in tumor angiogenesis is matrix metallopeptidase 9 (MMP-9)." (PMID 33081056, 2020). "Mmp9 is involved in a wide range of biological functions including macrophage differentiation, inflammation, bone metabolism, and tumor invasion." (PMID 32599940, 2020). "MMI-166, a third-generation inhibitor of MMP-2 and MMP-9, has shown to be significantly effective in reducing tumor cell proliferation and the formation of metastasis." (PMID 32392801, 2020). "Among the various MMP family members, the gelatin-degrading enzymes MMP-2 and MMP-9 are considered the tumor-invasive components as their expression levels are often up-regulated in advanced stages of cancer." (PMID 32984054, 2020). "The disruption of the basement membranes by the MMPs, such as MMP-9/-2, lead to the tumor cell migration and invasion, and thus play crucial roles in the EMT processes." (PMID 32466169, 2020). "Suppression of MMP-9 not only inhibits the invasiveness and metastasis of tumor cells, but can also affect angiogenesis and cell growth." (PMID 32328465, 2020). "MMP-9, which plays an important role in cancer cell invasion and tumor metastasis, is one of the most important members of the MMP family." (PMID 32698816, 2020). "For example, MMP-9 overexpression is often observed across numerous malignant tumor types, and MMP-9 has been investigated for its potential as a cancer biomarker." (PMID 33194731, 2020). "Tumor-associated macrophages secrete multiple angiogenic factors, e.g., vascular endothelial growth factor-A (VEGF-A) and matrix metalloproteinase 9 (MMP9), which induce blood vessel initiation and extension, as well as tumor cell metastasis to new sites." (PMID 33086476, 2020). "Previous studies elucidate that N-cadherin has a role in motility, invasion and metastasis by increasing MMP-9 production allowing tumour cells to penetrate the matrix barriers and to adhere to the endothelium." (PMID 31599393, 2020).
tumor (continued). "Hypoxia has been shown to induce the expression of MMP2 and MMP9, which are important molecules for tumor cell invasion and metastasis." (PMID 32993787, 2020). "NF‐κB–associated proteins involved in tumour progression, such as MMP‐2, MMP‐9, uPA, VEGF, XIAP and Cyclin D1, were all decreased by imipramine." (PMID 32149465, 2020). "The expression levels of PTEN, MMP2, and MMP9 often indicate invasive and metastatic ability of tumor cells." (PMID 32974191, 2020). "This is supported by the fact that upregulation of a NDRG3 paralogous, NDRG2, suppresses tumor invasion by inhibiting the matrix metalloproteinases MMP-9 and MMP-2." (PMID 33175867, 2020). "In this study, we established a novel human OSCC model in zebrafish body to observe tumor progression in a real-time manner and confirm the possible function of MMP-9 in vivo." (PMID 32382550, 2020). "The data rather convincingly show that tumor MMP9 expression drives PDAC progression, but systemic MMP9 ablation triggers invasive growth and metastasis by blocking MMP9-dependent tumor-inhibiting effects in the bone marrow." (PMID 32325664, 2020). "In vitro and in vivo experiments in human and experimental models of cancers reveal that the increased MMP9 expression is related to tumour progression." (PMID 32445177, 2020). "The good news is that inhibitors of HIV protease or reverse transcriptase and CXCR4 antagonists, which have been used for many years to counter HIV infection, effectively inhibit MMP-9 expression and tumor cell dissemination." (PMID 32630531, 2020). "Subsequently, neutrophils stimulate the proangiogenic activity of tumor cells at adjacent invading edges by producing MMP9." (PMID 33101283, 2020). "In ESCC, MMP-2 and MMP-9 contribute to tumor invasion and metastasis, and VEGFs including VEGF-A contribute to angiogenesis and are associated with high microvascular density and poor patient prognosis." (PMID 32457351, 2020). "Specifically, using Hyp-PDT prevents tumorigenesis by impeding tumor-promoting cytokines signaling and downregulating mediators of tumor metastasis-like cancer-derived matrix metalloproteinase-9 (MMP-9)." (PMID 32340275, 2020). "This potentiates and localizes MMP-9-promoted breakdown of the vessel wall required for tumor cell extravasation." (PMID 32630531, 2020). "A study performed on A549 NSCLC cells demonstrates that upregulation of MMP-9 promotes tumor cell migration and increases invasiveness." (PMID 33262947, 2020). "Human peritoneal mesothelial cells (HPMCs) uptake exosomes containing CD44 that are released from ovarian cancer cells; therefore, CD44 is elevated in the HPMCs and induced MMP9 secretion which promote tumor invasion." (PMID 32499786, 2020). "The HIV-reverse transcriptase inhibitors zidovudine and lamivudine can downregulate MMP-9 expression in normal or tumor cells, weaken MAPK/ERK or PI3K/AKT phosphorylation, reduce nitric oxide production and impair angiogenesis." (PMID 32630531, 2020). "What is more, MMP-9 has been found to be significantly overexpressed in TC compared with adjacent non-tumor tissues." (PMID 32698816, 2020). "Western blotting results indicated that the protein level of BRD4, c-Myc, CyclinD1, CDK4, MMP-2, MMP-9, Vimentin and N-cadherin were all decreased while E-cadherin was increased in the tumor with circCELSR1 knockdown." (PMID 32640974, 2020). "The RNA interference (RNAi)-mediated knockdown of MMP3 and/or MMP9 significantly attenuated tumor growth and metastasis in the tumor allograft mouse model." (PMID 32429403, 2020). "The absence of IFN-β augmented intratumoral infiltration of CXCR2-expressing neutrophils, which abundantly produced VEGF and MMP-9 and as a consequence, neutrophil depletion reduced tumor angiogenesis." (PMID 32422991, 2020). "Using this approach, we have established the role of a MAPK7/MMP9 signalling axis in recruiting TAMs to PBC tumours to induce lung metastasis." (PMID 32655131, 2020).